PDGFRB (platelet derived growth factor receptor beta)
Diseases named in the same sentence as PDGFRB in open-access papers (continued):
Sharing a sentence is not in itself a finding about the gene and the disease.
diabetes (21 papers, 2012 to 2026). "Previous studies have shown increased renal expression of PDGFRβ in patients with diabetes and in rodent kidneys with diabetic kidney disease." (PMID 39761275, 2025). "IB4 and NG2 immunofluorescence staining showed pericyte-specific deletion of Mettl3 significantly decreased diabetes-induced pericyte dysfunction in Mettl3f/f; Pdgfrβ-Cre mice compared with the control group." (PMID 34987645, 2022). "TECs in diabetes undergo endothelial-to-mesenchymal transition and exhibit reduced PDGFB expression, while Leydig and testicular peritubular cells downregulate PDGFRB, collectively weakening intercellular connectivity." (PMID 41643060, 2026). "Consistently, both NG2 and PDGFRβ staining demonstrated reduced pericyte coverage of retinal vessels upon the combination of FTO overexpression and diabetes." (PMID 38297099, 2024). "Using brilliant databases and bioinformatics tools, we identified GABBR1-centered ceRNAs formed by PDGFRB and WNT2B via hsa-miR-19-3p and RNA-RNA interactions with HMGA1 and SMARCA4 as shared molecules between diabetes and viral infection." (PMID 37969011, 2023). "Therefore, we concluded that we obtained a shared ceRNA network between diabetes and viral infections, which consisted of GABBR1, PDGFRB, WNT2B, and hsa-miR-19b/a-3p." (PMID 37969011, 2023). "Similarly, anti-PDGFRB and anti-IGF1R therapy in COVID-19 patients with or without pre-existing diabetes require further investigations." (PMID 34067609, 2021).
Alzheimer disease (20 papers, 2010 to 2025). A progressive, neurodegenerative disease characterized by loss of function and death of nerve cells in several areas of the brain leading to loss of cognitive function such as memory and language. "PDGFRB is a pericyte marker and deficient PDGFRB signaling is a prominent feature of the blood-brain barrier breakdown described in Alzheimer’s disease." (PMID 36818567, 2023). "Numerous studies investigated the role of PDGFRB in the development of Alzheimer’s disease." (PMID 36389665, 2022). "Our recent post-mortem studies indicate that biochemical markers of pathological hypoperfusion and reduced oxygenation of the cerebral cortex in Alzheimer’s disease and vascular dementia are associated with elevated levels of amyloid-β42, EDN1, and fibrinogen, and reduced PDGFRβ." (PMID 33723589, 2021). "Established markers of Alzheimer’s disease and neurodegeneration, including TREM2, SAA1, CHIT1, CRP and PDGFRB demonstrated strong correlations (r > 0.8) in the comparison with SomaLogic measurements." (PMID 41250190, 2025). "Here, we show that MAG:PLP1 and PDGFRβ were significantly reduced, at an early stage i.e. BSIII–IV, in Alzheimer’s disease indicating vascular dysfunction from an early to intermediate stage of disease." (PMID 33723589, 2021). "Cortical platelet-derived growth factor receptor-β (PDGFRβ), a pericyte marker, was reduced, and endothelin-1 (EDN1) level was increased in Alzheimer’s disease; these were related to amyloid-β level and disease progression and only modestly affected by systemic infection." (PMID 33723589, 2021). "PDGFRβ tended to decline with increasing amyloid-β42 in Alzheimer’s disease brains in the absence of infection and to increase slightly in the presence infection but none of these trends was significant." (PMID 33723589, 2021). "Pericyte loss and deficient vascular platelet-derived growth factor receptor-β (PDGFRβ) signaling are prominent features of the blood–brain barrier breakdown described in Alzheimer’s disease (AD) that can predict cognitive decline yet have never been studied in the retina." (PMID 32043162, 2020).
Cognitive impairment (20 papers, 2011 to 2026). Abnormal cognition is characterized by deficits in thinking, reasoning, or remembering. "Prior studies have reported an association of CSF PDGFRβ with cognitive impairment in neurodegenerative disorders, both in cross-sectional and longitudinal studies." (PMID 40239464, 2025). "In a subset of subjects where MMSE scores were available, we identified a significant correlation between retinal PDGFRβ loss and cognitive impairment." (PMID 32043162, 2020). "Early and progressive reductions in vascular platelet-derived growth factor receptor-β (PDGFRβ) has been reported in patients with mild cognitive impairment, and AD was significantly associated with an increased retinal vascular load of Aβ, leading to BRB abnormalities." (PMID 37686379, 2023). "AD and other dementia patients frequently show focal changes in brain microcirculation which have been associated with cognitive impairments; PDGFRβ+/– mice have significantly reduced capillary length which also coincides with an age-dependent decrease in memory and learning tasks." (PMID 31866833, 2019). "Mild cognitive impairment and dementia patients showed lower plasma PDGFRβ than cognitively unimpaired individuals." (PMID 41530860, 2026). "Moreover, loss-of-function mutations in the PDGFB gene within the endothelium or in the PDGFRB gene within pericytes can cause primary familial brain calcification, which is characterized by pericyte loss and neurological symptoms including motor and cognitive impairments." (PMID 37958635, 2023). "PDGFRβ was measured in the CSF of 771 participants with cognitively unimpaired (CU, n = 408), mild cognitive impairment (MCI, n = 175), and dementia (n = 188) from the Swedish BioFINDER-2 cohort." (PMID 37137722, 2023). "Because BBBb precedes other detectable pathological changes, biomarkers such as platelet-derived growth factor receptor beta (PDGFRb), can serve for early detection prior to the onset of cognitive impairment facilitating early therapeutic interventions." (PMID 36316783, 2022). "Here, the lack of cognitive data or assessment of retinal vascular Aβ and vascular PDGFRβ in mice younger than 4 months limits our ability to determine how early vascular pathology occurs in the retina and its relationship to cognitive deficits." (PMID 33228786, 2020). "Evaluation of postmortem retinas from a cohort of 56 human donors revealed an early and progressive decrease in vascular PDGFRβ in mild cognitive impairment (MCI) and AD compared to cognitively normal controls." (PMID 32043162, 2020). "In individuals with mild cognitive impairment, as well as in PDGFRβ+/– mice, soluble PDGFRβ (sPDGFRβ) increases in the cerebrospinal fluid (CSF) following pericyte loss, suggesting sPDGFRβ may serve as a biomarker for pericyte death." (PMID 31866833, 2019). "Furthermore, a decrease in the expression of the pericyte marker platelet-derived growth factor receptor beta (PDGFRβ) results in impaired BBB function, which subsequently contributes to cognitive deficits." (PMID 39941141, 2025).
acute myeloid leukemia (19 papers, 2012 to 2026). Acute myeloid leukemia (AML) is a group of neoplasms arising from precursor cells committed to the myeloid cell-line differentiation. "Recent evidence indicates that FTO via m6A demethylation of PDGFRB mRNA enhances PDGFRβ expression in acute myeloid leukemia cells." (PMID 40429638, 2025). "Crenolanib is a potent class III receptor tyrosine kinase inhibitor including PDGFRB, with minimal toxicity, whose therapeutic efficacy has already been validated through clinical trials in GIST and human acute myeloid leukemia." (PMID 28435517, 2017). "The pathologic diagnoses of PDGFRB associated mutations have included chronic myelomonocytic leukemia (CMML), chronic eosinophilic leukemia (CEL), atypical CML, myelodysplastic syndrome (MDS), and acute myeloid leukemia (AML)." (PMID 23936692, 2013). "Linifanib is clinically active in patients with HCC, acute myeloid leukemia (AML), renal cell cancer, and NSCLC, inhibiting cell proliferation, tumor growth, and metastases in ES cells in xenografts by suppressing PDGFRβ and c-kit activation." (PMID 32754598, 2020).
Hypertension (18 papers, 2010 to 2025). The presence of chronic increased pressure in the systemic arterial system. "Human autopsy studies in patients with longer-lasting hypertension likewise reported pericyte injury, that is, lower parenchymal levels of PDGFRβ, together with BBB leaks, that is, parenchymal fibrinogen deposition." (PMID 39495252, 2024). "Chronic pericyte exposure to TNFα, IFN-γ, or IL-1β (e.g., during the longer course of hypertension) compromises pericyte function, leading to BBB disruption, which is mediated through the decrease of angiopoietin 1 or platelet-derived growth factor receptor β (PDGFRβ) and its signaling." (PMID 39495252, 2024).
acute lymphoblastic leukemia (15 papers, 2016 to 2025). Leukemia with an acute onset, characterized by the presence of lymphoblasts in the bone marrow and the peripheral blood. "For example, the RUNX l gene is the second gene found to be rearranged with ETV6 after PDGFRB, and the ETV6 / RUNXl fusion gene is considered the most common fusion gene in early childhood acute lymphoblastic leukemia." (PMID 39634885, 2024). "Recent studies revealed that a substantial proportion of patients with high-risk B-cell precursor acute lymphoblastic leukemia (BCP-ALL) harbor fusions involving tyrosine kinase and cytokine receptors, such as ABL1, PDGFRB, JAK2 and CRLF2, which are targeted by tyrosine kinase inhibitors (TKIs)." (PMID 27176795, 2016).
thyroid cancer (15 papers, 2011 to 2025). "In addition to the activation of HER family members, there was upregulation of PDGFRβ in response to vemurafenib in thyroid cancer cell lines." (PMID 36624452, 2023). "In veterinary medicine, the role of PDGFR, particularly PDGFRβ, is gaining recognition as a therapeutic target, evidenced by its expression in canine malignant tumors such as hemangiosarcomas, AGASACs and thyroid carcinomas, and urinary bladder transitional cell carcinomas." (PMID 41472102, 2025). "Actually, inhibition of the BRAFV600E/MEK/ERK axis in thyroid cancer cells also results in reactivation of a variety of RTKs such as HER2/HER3, platelet-derived growth factor receptor-beta (PDGFRβ), and EGFR." (PMID 36624452, 2023).
dermatofibrosarcoma protuberans (14 papers, 2011 to 2024). Dermatofibrosarcoma protuberans (DFSP) is a rare infiltrating soft tissue sarcoma, generally of low grade malignancy, arising from the dermis of the skin and characteristically associated with a specific chromosomal translocation t(17;22). "In the dermatofibrosarcoma protuberans, the fusion of the collagen type I alpha 1 (COL1A1) gene with the PDGFB gene caused PDGFBB and its receptor (PDGFRβ) autocrine stimulation and cell proliferation." (PMID 38378786, 2024). "Gene rearrangements involving PDGFRB have also been described, such as the one present in dermatofibrosarcoma protuberans a benign proliferative condition, in which the fusion COL1A1-PDGFB makes cells express more PDGFRB in a constitutive fashion." (PMID 29455659, 2018). "Imatinib mesylate, targeting platelet-derived growth factor receptor beta, has clinical potential in dermatofibrosarcoma protuberans." (PMID 23199263, 2012). "Imatinib has also demonstrated clinical benefit in the metastatic setting for dermatofibrosarcoma protuberans (DFSP) through inhibiting the activation of platelet derived growth factor receptor beta (PDGFR-β)." (PMID 27732970, 2017). "Noteworthy, dermatofibrosarcoma protuberans (DFSP), a rare STS subtype with a local infiltrative growth pattern, carries a COL1A1/PDGFB fusion-gene that is responsible for PDGFRβ autocrine activation and subsequent tumorigenesis." (PMID 32532153, 2020). "Imatinib was found to specifically target PDGFRB tyrosine kinase, and so its use was approved for treating COL1A1-PDGFRB-positive dermatofibrosarcoma." (PMID 32317857, 2020).
fibrosis (14 papers, 2006 to 2026). the formation of excess fibrous connective tissue in an organ or tissue in a reparative or reactive process. "In the CCl4 fibrosis model, approximately half of the Thy 1.2 positive cells were also labelled by PDGFRβ-P2A-CreER." (PMID 37147343, 2023). "Platelet-derived growth factor receptor beta (PDGFRβ+) cells constitute a major population of contractile myofibroblasts in the lung following bleomycin-induced fibrosis." (PMID 29813125, 2018). "Fibrosis-associated tdTomato was found only in PDGFRβ- and Tcf21-reporter mice, but not in NG2-and SMMHC-tdTomato mice." (PMID 39829679, 2025). "CCDC80, LAMA4, PDGFRB, PODN, and SPARC are potential mediators of intestinal fibrosis due to common expression among ileal and colonic strictures." (PMID 40398622, 2025). "Conversely, PDGFRβ activation by intradermal injection of PDGF-BB in mice significantly aggravates bleomycin-induced dermal thickening, vascular alterations, and monocyte/macrophage infiltration, exacerbating skin injury and fibrosis." (PMID 35409263, 2022).
liver cancer (14 papers, 2019 to 2025). An epithelial or non-epithelial malignant neoplasm that arises from the liver. "We also find increased expression of myofibroblasts and fibrosis markers (PDGFRB, COL1A1, COL3A1, COL11A1) and early liver cancer markers (GPC3 and MUC1)." (PMID 41065540, 2025). "EMT- and metastasis-related markers (ACTA2 and PDGFRB) were expressed at similar levels in the Matrigel group, the Liver ECM group, and liver cancer tissue." (PMID 40852642, 2025). "We then confirmed that liver cancer organoids expressed liver cancer-specific characteristics by checking the expression of liver cancer differentiation markers (AFP and KRT19), proliferation marker (Ki67), and EMT activation markers (PDGFRB and α-SMA)." (PMID 40852642, 2025). "The PDGF/PDGFRB signaling we observed in the low MC region activates the downstream lymphocyte-activation gene 3 (LAG3)/fibrinogen-like protein 1 (FGL1) immunosuppressive axis, adding complexity to liver cancer immune evasion analysis." (PMID 39015573, 2024). "On the basis of miR‐378a enhancing the sensitivity of liver cancer to sorafenib by targeting VEGFR, PDGFRβ and c‐Raf31, we further confirmed that the expression of miR-378a-3p was decreased in sorafenib-resistant HCC cells and identified IGF1R as the target gene of miR-378a-3p." (PMID 32754282, 2020).
ischemic stroke (13 papers, 2016 to 2025). A stroke disorder caused by obstruction of blood flow to the brain, due to thrombotic (local blood clot formation) or embolic (due to a blood clot or other material traveling from another site) event. "In the lesion core of subcortical ischemic stroke lesions in humans, we found nearly all PDGFRβ+ stromal cells associated with the vascular wall." (PMID 34535655, 2021). "PDGFRβ+ fibroblasts co-expressing PDGFRα, which are essentially associated with the large pial penetrating vasculature, and PDGFRβ+ pericytes, which are essentially associated with parenchymal microvasculature, both have been reported to contribute to fibrotic scar formation after ischemic stroke." (PMID 38769116, 2024). "PDGF-D a specific ligand of PDGFRβ is expressed in the brain, yet its regulation and role in ischemic stroke pathobiology remains unexplored." (PMID 38769116, 2024). "Deregulation of PDGFRβ signaling in ischemic stroke attenuates pericytes interaction with endothelial cells, leading to injury exacerbation associated with impaired angiogenesis and altered CBF restoration." (PMID 38769116, 2024). "This suggests that reactive PDGFRβ+ pericytes contribute to IGF1 production at the lesion site after ischemic stroke." (PMID 38769116, 2024). "Using multiplex RNAscope® F.I.S.H, we showed that PDGFRβ mRNA expression was slightly reduced at the lesion site 24 h after ischemic stroke followed by an increased expression that peaked at 1 week." (PMID 38769116, 2024). "PDGFRβ expression is induced after ischemic stroke, and contributes to subacute tissue structural repair." (PMID 38769116, 2024). "Although PDGFRβ protein expression was reportedly shown to be induced after ischemic stroke, little is known about its spatiotemporal transcriptomic regulation." (PMID 38769116, 2024). "Our analysis revealed that PDGFRα+ and perivascular tdTomato+ cells (i.e. deriving PDGFRβ+ cells) constitute two distinct populations at the lesion site 1 week after ischemic stroke." (PMID 38769116, 2024). "Deregulation of PDGFRβ signaling aggravates brain damage and neurological deficits after ischemic stroke." (PMID 38769116, 2024). "The vascular redistribution of PDGFRβ+ pericytes upon RGS5 depletion after ischemic stroke enhances angiogenesis, while reducing microvascular permeability." (PMID 38769116, 2024). "No study has evaluated how Dl-3-n-butylphthalide affects the ferroptosis SLC7A11/GSH/GPX4 signal pathway and blood–brain barrier (BBB) PDGFRβ/PI3K/Akt signal pathways in the rat middle cerebral artery occlusion/reperfusion (MCAO/R) model of ischemic stroke." (PMID 36909944, 2023). "Type A pericytes are the main source of PDGFRβ-expressing stromal cells in mouse models of penetrating and non-penetrating spinal cord injuries, traumatic brain injury, ischemic stroke and MS, but contribute less extensively to tumor stroma." (PMID 34535655, 2021). "Our results demonstrate that PDGF-D expression is induced in brain endothelial cells in the subacute phase of ischemic stroke along with PDGFRβ, and its expression contributes to the spontaneous protection of neurovascular functions by rescuing the vascular protective properties of pericytes." (PMID 38769116, 2024). "In contrast to striatal ischemic strokes, 60–70% of the recombined cells that expressed PDGFRβ were no longer associated to the vascular wall in the lesion core." (PMID 34535655, 2021). "To determine whether microglia originate, at least in part, from reactive PCs, we first investigated the localization of PDGFRβ+ cells following ischemic stroke." (PMID 26952098, 2016). "Under pathological conditions, mural cells in the immediate postacute phase (SE, ischemic stroke, and head trauma) require support from the PDGFRβ activation; hence, the inflammatory involvement of PDGFRβ may be relevant in long-term progression as well as in chronic stages." (PMID 34209145, 2021). "We then investigated whether PDGFRβ+ PCs express Iba1 following ischemic stroke." (PMID 26952098, 2016).
ischemic stroke (continued). "Thus, we next examined whether PDGFRβ+ PCs express the stem cell marker nestin following ischemic stroke." (PMID 26952098, 2016). "Recombined reactive astrocytes, co-expressing EYFP or tdTom and GFAP (but not PDGFRβ), could be observed in the lesion rim as part of the glial scar across all ischemic stroke models." (PMID 34535655, 2021). "However, PDGF-D impact on PDGFRβ+ cells other than pericytes could not be excluded, but the changes could not be detected 2 weeks after ischemic stroke." (PMID 38769116, 2024).